U2AF1 (U2 small nuclear RNA auxiliary factor 1)
Diseases named in the same sentence as U2AF1 in open-access papers (continued):
Sharing a sentence is not in itself a finding about the gene and the disease.
myelofibrosis (12 papers, 2019 to 2023). A partial or complete replacement of the bone marrow stroma by fibrous tissue. "U2AF1 occur in 16% of PMF, and PV and ET patients harboring U2AF1 mutations have an inferior myelofibrosis-free survival compared to U2AF1 wild-type patients." (PMID 35562964, 2022). "SRSF2, ASXL1 and U2AF1 mutations predict inferior survival in primary myelofibrosis, independently of other risk factors." (PMID 35740649, 2022). "In myelofibrosis, patients presenting with a citopenias involving one or more hematopoietic lineages are defined as MF with myelodepletive phenotype and presented U2AF1 mutations as a distinct molecular marker." (PMID 35562964, 2022). "Furthermore, mutations in both SRSF2 and U2AF1 correlated with transformation from PV and ET to myelofibrosis and development of other hematological malignancies." (PMID 37637067, 2023).
lung carcinoma (9 papers, 2016 to 2022). "Although U2AF1 mutations have been implicated as driver mutations in lung cancer and MDS, the role of these mutations in disease progression has remained elusive." (PMID 33137094, 2020). "Analysis of the distribution of these U2AF1 mutations across the protein revealed a single, dominant hotspot at S34F that comprised the majority of mutations in lung cancers (81%)." (PMID 31836708, 2019). "We have asked how the common S34F mutation in the splicing factor U2AF1 regulates alternative splicing in lung cancer, and why wild-type U2AF1 is retained in cancers with this mutation." (PMID 27776121, 2016). "Mutations in some RNA splicing factors, such as SF3B1, SRSF2, and U2AF1, have been found to be involved in the pathogenesis of cancers, such as lung cancer, breast cancer, and pancreatic cancers." (PMID 36371223, 2022). "Therefore, the functional significance of U2AF1 mutations in lung cancer remains largely unknown." (PMID 31836708, 2019). "While U2AF1 is an essential gene required for cell survival, this finding suggests that there may be future opportunities for U2AF1-directed therapeutic targeting in lung cancers." (PMID 31836708, 2019). "Finally, unlike in MDS/AML, U2AF1 S34Y variants are exceedingly rare in lung cancers, as are mutations in other components of the spliceosome." (PMID 31836708, 2019).
anemia (6 papers, 2017 to 2023). A reduction in the number of red blood cells, the amount of hemoglobin, and/or the volume of packed red blood cells. "We suggest that aberrant splicing of H2AFY leads to impaired erythropoiesis and may play a role in the anemia observed in MDS patients with U2AF1 mutation." (PMID 28436936, 2017). "In addition, mutations in U2AF1 were associated with anemia and thrombocytopenia, and SRSF2 with anemia." (PMID 32781570, 2020). "In addition, previous studies demonstrated that U2AF1 mutant is prone to anemia and thrombocytopenia, and S34F mutant of U2AF121 can have reduced erythropoiesis and abnormal granulo-monocyte differentiation via regulating the downstream target gene H2AFY and STRAP to form abnormal splicing." (PMID 33122737, 2020).
breast carcinoma (5 papers, 2017 to 2023). "U2AF1 has been reported to be one of the most common spliceosome factors affected by somatic point mutations that induce alternative mRNA splicing and contribute to breast cancer development and metastases." (PMID 33330095, 2020).
chronic lymphocytic leukemia (5 papers, 2015 to 2024). "In oncohematology, numerous spliceosome gene mutations have been identified in chronic lymphocytic leukemia (CLL), myelodysplastic syndromes, and lymphomas; among the most well-known of these are those involving SF3B1, U2AF1, and SRSF2." (PMID 26937306, 2015). "For example, mutations in SF3B1, U2AF1, SRSF2, and zinc finger CCCH-type, RNA-binding motif and serine/arginine-rich 2 (ZRSR2) were found in a variety of hematological malignancies, including myelodysplastic syndromes (MDSs) and chronic lymphocytic leukemia (CLL), and they are mutually exclusive." (PMID 32188117, 2020).
primary myelofibrosis (5 papers, 2020 to 2025). Myelofibrosis with myeloid metaplasia is a myeloproliferative disease with annual incidence of approximately 1 case per 100,000 individuals and age at diagnosis around 60 (an increased prevalence is noted in Ashkenazi Jews). "We previously reported U2AF1 mutations were associated with grades-2/-3 bone marrow fibrosis." (PMID 36224330, 2022). "Thirteen genes including ASXL1, U2AF1, SRSF2, SF3B1, and ZRSR2 had significantly higher mutation frequencies in primary myelofibrosis (PMF) compared with essential thrombocythemia and polycythemia vera; this difference distinguished PMF from MPN and likened it to MDS." (PMID 33117717, 2020). "Gene mutations in epigenetic regulators (ASXL1, TET2, DNMT3A and EZH2) and RNA splicing (U2AF1 and SRSF2) were considered as the additional subclonal mutations and cooperated with the MPN driver mutation (JAK2, MPL or CALR) to play a key role in the pathogenesis of primary myelofibrosis." (PMID 35740649, 2022).
Thrombocytopenia (5 papers, 2020 to 2023). A reduction in the number of circulating thrombocytes. "Although the prevalence of CH was not increased in thrombocytopenia cases compared with their controls (37.9% vs 39.3%; P = 0.639), mutations in spliceosome genes (SF3B1, SRSF2, U2AF1) were significantly enriched in thrombocytopenia cases (P = 0.007)." (PMID 36698617, 2023). "Spliceosome mutations (SF3B1, SRSF2, and U2AF1) were enriched in individuals with thrombocytopenia compared with their matched controls (3.4% vs 1.1%; P = 0.007)." (PMID 36698617, 2023). "Among the RNA splicing genes, U2AF1 is vital for hematopoiesis and is associated with thrombocytopenia in PMF." (PMID 36139644, 2022). "In the PMF group, we found that the U2AF1 mutation was associated with thrombocytopenia." (PMID 36139644, 2022). "In the pre-PMF group, we found that thrombocytopenia, ASXL1, MPL, U2AF1, SETBP1, and SRSF2 mutations were associated with inferior overall survival." (PMID 36139644, 2022). "Thrombocytopenia arises from multiple factors, including displacement of medullary thrombopoietic tissue by fibrosis, JAK-inhibitor induced myelosuppression, and genetic factors (U2AF1 mutations and complex/high-risk cytogenetics)." (PMID 37444441, 2023).
pancreatic cancer (4 papers, 2011 to 2023). "Validating these findings, we found that genes encoding for the splice factors RBM10, SF3B1, and U2AF1 are also frequently mutated in the Pancreatic Cancer Canadian (PACA-CA) cohort." (PMID 37823551, 2023). "Since lower U2AF1 expression predicted poorer prognosis, we knocked down U2AF1 in BxPC-3 and AsPC-1 pancreatic cancer cells using shRNA, which significantly reduced both the mRNA and protein levels of U2AF1, and then measured the expression of CD44V3." (PMID 36292918, 2022). "In this study, we examined another splicing factor, U2AF1, in pancreatic cancer progression and found it was significantly downregulated in pancreatic tumor tissues." (PMID 36292918, 2022). "Mechanistically, CD44V3 expression was downregulated by splicing factor U2AF1, an important component of the spliceosome, and the expression of U2AF1 was reduced in pancreatic cancer cells and tissues." (PMID 36292918, 2022). "Moreover, Kaplan–Meier analysis showed that higher U2AF1 levels predicted better OS for pancreatic cancer patients." (PMID 36292918, 2022). "To this end, we examined the expression of U2AF1 in adjacent normal tissues and pancreatic tumor tissues by RT-qPCR, to explore whether U2AF1 was involved in the regulation of CD44V3 expression." (PMID 36292918, 2022). "Interestingly, U2AF1 expression level was negatively correlated with CD44V3 expression level in pancreatic tumor tissues." (PMID 36292918, 2022). "Moreover, knockdown of U2AF1 could significantly increase the expression level of CD44V3, which indicates that the splicing and expression of CD44V3 are regulated by U2AF1 in pancreatic cancer cells." (PMID 36292918, 2022). "CD44V3 splicing was regulated by U2AF1 and downregulation of U2AF1 enhanced CD44V3 expression, which promoted pancreatic cancer progression." (PMID 36292918, 2022). "In future studies, it would be interesting to look into methods to modulate the activation of the U2AF1 and/or CD44V3 axis for pancreatic cancer treatment." (PMID 36292918, 2022).
chronic myelomonocytic leukaemia (3 papers, 2019 to 2025). "PTPN11mut was more common in myelomonocytic and monocytic leukemia, and was more likely to co‐mutate with KRAS, KMT2C, NRAS, U2AF1, NOTCH1, IKZF1, and USH2A mutations than PTPN11wt." (PMID 37937729, 2023).
bladder cancer (2 papers, 2014 to 2020). "We first downloaded the mRNA expression data of normal and bladder cancer tissues from TCGA database and analyzed the mRNA expression of a total of 97 RNA splicing proteins (including SRSF family, RBM family, HNRNP family, SF3B1, PRMT5, PUF60, U2AF1, and ZRSR2) between normal and carcinoma tissues." (PMID 33117697, 2020).
VEXAS syndrome (2 papers, 2024 to 2025). An adult-onset inflammatory disease that affects only males and is caused by somatic, not germline, mutations. "NGS testing revealed mutations in TET2, U2AF1, and UBA1, leading to the diagnosis of low-risk MDS (IPSS-R of 2.5) and VEXAS syndrome." (PMID 38398362, 2024).
acute lymphoblastic leukemia (1 paper, 2023). Leukemia with an acute onset, characterized by the presence of lymphoblasts in the bone marrow and the peripheral blood. "The same splicing factor was reported by another study, which identified that low levels of U2AF1 mRNA can be used as a prognosis for risk stratification in children with T-lineage acute lymphoblastic leukemia." (PMID 36609432, 2023).
bone marrow failure (1 paper, 2022). "The HSPC ablation caused by U2af1 deletion may lead to bone marrow failure and early lethality in U2af1-deficient mice." (PMID 36139566, 2022).
chronic myeloid leukemia (1 paper, 2022). "Remarkably, a large number of U2AF1 mutational landscapes in various hematologic tumors have been reported, including MDS, MDS/MPN, MPN, AML, and chronic myeloid leukemia (CML)." (PMID 36139566, 2022).
cystic fibrosis (1 paper, 2020). Autosomal recessive disorder caused by pathogenic variants in the CFTR gene (cystic fibrosis transmembrane conductance regulator), which encodes a chloride and bicarbonate channel expressed in epithelial cells, and follow the diagnosis criteria. "Application to cystic fibrosis and spinal muscular atrophy (SMA) identifies established CF modifiers and a new putative modifier of SMA, U2AF1." (PMID 33438800, 2020).
glioblastoma (1 paper, 2022). The most malignant astrocytic tumor (WHO grade IV). "Driver mutations have been found in several RNA-binding proteins (e.g., SF3B1, U2AF1, SRSF2, HNRNPA2B1, SRRM2) in cancers ranging from blood malignancies to glioblastoma, but several questions remain regarding how widely this group of proteins and their targets are involved in cancer." (PMID 35581644, 2022).
glioma (1 paper, 2019). A benign or malignant brain and spinal cord tumor that arises from glial cells (astrocytes, oligodendrocytes, ependymal cells). "In a human glioma malignancy study the circRNA U2 auxiliary factor 35 kDa subunit (circ-U2AF1) was found upregulated along with neuro-oncological ventral antigen 2 (NOVA2)." (PMID 31080413, 2019).
hepatocellular carcinoma (1 paper, 2018). A malignant tumor that arises from hepatocytes. "Our results support the emergent role of the spliceosome pathway in prostate carcinogenesis with TRA2A and U2AF1: TRA2A is deregulated in different cancers such as hepatocellular carcinoma, pediatric pineal germinomas and triple-negative breast cancer (TNBC)." (PMID 29805743, 2018).
Immunodeficiency (1 paper, 2023). Failure of the immune system to protect the body adequately from infection, due to the absence or insufficiency of some component process or substance. "It is also unknown if the immunodeficiency induced by MDS-associated U2AF1 mutations is unique to U2AF1 or if other spliceosome mutations induced similar defects." (PMID 37591942, 2023). "In the current study, we found that mice engineered to express U2AF1-S34F but not wild type U2AF1 exhibit a profound immunodeficiency, likely due to neutrophil chemotaxis defects induced by this MDS-associated spliceosome mutation." (PMID 37591942, 2023).
cancer (80 papers, 2011 to 2026). A tumor composed of atypical neoplastic, often pleomorphic cells that invade other tissues. "Currently, the prognosis of U2AF1 mutations in cancer, particularly in haematological diseases, remains to be fully elucidated." (PMID 40066790, 2025). "Analysis of the Catalogue of Somatic Mutations in Cancer (COSMIC) data showed that missense mutations of U2AF1 accounted for 80% of tumor samples." (PMID 38883705, 2024). "Many of the affected events were cassette exons possessing weak 3′ splice sites with a preference for U versus C at the −3 position, reminiscent of exons differentially affected by U2AF1 S34F/Y mutations found in numerous cancers." (PMID 37673460, 2023). "Nonetheless, large cancer databases, including the National Cancer Institute's Genomic Data Commons, are likely missing many U2AF1 mutations due to this artefact." (PMID 35041928, 2022). "Two studies based on the analysis of the RNA-seq data of AML cases from TCGA found that U2AF1 mutations lead to aberrant gene splicing events in important biological pathways, such as cell cycle progression, RNA processing, and other cancer-related genes." (PMID 36139566, 2022). "The cancer-causing mutations in U2AF1 typically affect either S34 or Q157 within the zinc finger domains of the U2AF1 protein, resulting in changes in U2AF1 3′ splice site recognition." (PMID 34196950, 2022). "Numerous studies have focused on uncovering the effects of U2AF1 mutations on the downstream target genes and biological pathways in myeloid cancers to uncover the driving effects of U2AF1 mutations on cancer progression." (PMID 36139566, 2022). "Multiple mutations in U2AF1 can cause irregular expression patterns of some genes affected in cancer pathogenesis." (PMID 36251702, 2022). "Mutations in U2AF1 contribute to cancer progression and have been reported in several different cancer types including CRC56, while MBNL2 was reported as tumour suppressor in hepatocarcinogenesis." (PMID 35552415, 2022). "All but two of these RBPs (FXR1 and PUM1) are splicing factor genes and U2AF1 exhibited significant driver mutation patterns across a wide variety of cancer types." (PMID 32532357, 2020). "In sum, this study uncovered a novel, to our knowledge, dependence of the cancer-associated U2AF1 mutations on ribosome biogenesis to maintain a highly proliferative state." (PMID 33137094, 2020). "U2AF1 is a common mutational target in several cancer types, such as MDS where 11% of cases are mutated." (PMID 27602765, 2016). "To test the function of cancer-associated U2AF1 mutations in NSE splicing, we performed reconstitution experiments with wild-type and mutated U2AF35 constructs that were cotransfected with the C minigene into cells (mock)-depleted of U2AF35." (PMID 26732650, 2016). "In contrast, wild-type U2AF1 is required for cell viability, consistent with the retention of a wild-type allele in human cancers carrying common U2AF1 mutations." (PMID 27776121, 2016). "We characterized a recurrent mutation in the spliceosome member U2AF1 and demonstrated its impact on alternative splicing of cancer-relevant genes, further suggesting the importance of aberrant splicing in leukemogenesis." (PMID 27602765, 2016). "EWAS in the 15 MZ pairs was performed using the same approach as the analyses in the 41 MZ twin pairs, and the top-ranked results included signals in the promoters (within 200 bp of the TSS) of genes COX7C and U2AF1 that have been previously linked to cancer." (PMID 26798410, 2016). "We find a significant overlap of 165 splicing changes upon induction of U2AF1 S34F in HeLa cells and splicing changes in human cancers with U2AF1 S34F/Y mutations (Fisher's exact test, P<2.2e-16)." (PMID 24498085, 2014). "We have found that a single point mutation in U2AF1 that is recurrent in multiple human cancers alters this kinetic balance to favor post-transcriptional splicing of both the β-globin reporter and also endogenous FXR1 mRNAs." (PMID 25271374, 2014).